NFKBIA (NFKB inhibitor alpha)
Diseases named in the same sentence as NFKBIA in open-access papers (continued):
Sharing a sentence is not in itself a finding about the gene and the disease.
tumor (continued). "In addition, studies on miR-196b-5p elucidated that miR-196b-5p targets and negatively regulates NFKBIA to accelerate the growth of NSCLC tumor cells." (PMID 38627774, 2024). "Usually, NFKBIA functions as a tumour suppressor and has the potential to be introduced as a novel anti-tumour agent, whether it can reverse pulmonary vascular remodeling in PAH is not yet clear." (PMID 36690956, 2023). "Reduced survival can be found in the NFKBIA deletion or low expression tumours." (PMID 37775993, 2023). "The expression of GRAMD1C, NFKBIA, and ACSS2 was significantly higher in normal tissues than in tumour tissues (P < 0.001, P = 0.0096, and P < 0.001, respectively), which indicated that CD24 and INHBA were risk genes and that GRAMD1C, NFKBIA, and ACSS2 were protective genes." (PMID 35999846, 2022). "In addition, genes that were upregulated in tumor-derived iCAFs were associated with the regulation of the inflammatory response, namely, IL6ST, NFKBIA, NT5E, SERPINF1, and NFKBIZ, suggesting that they play roles in communicating with immune cells." (PMID 34976204, 2022). "NME2 and NFKBIA represent putative tumor suppressor factors for future studies." (PMID 33424926, 2020). "Because of this inhibition ability, NFKBIA has long been considered as a tumor suppressor." (PMID 33424926, 2020). "Two cell lines, NS 462 and NS 470, showed heterozygous loss of NFKBIA in the complete medium, not detected in the original tumor: notably, the deletion was absent in the modified medium." (PMID 24330732, 2013). "In the subset of tumours suited for quantitative PCR analyses, we profiled the mRNA expression of RELA (encoding for RelA/p65) and a number of NF-κB target genes, such as BCL2L1 (Bcl-xL), CCND1 (Cyclin D1), CCND2 (Cyclin D2) and NFKBIA (IκBα)." (PMID 17622249, 2007). "Likewise, increased expression of NF-κB target gene NFkbia is consistent with BA treatments inducing M1-like classically activated macrophages with inflammatory functions and increased Complement-7 (C7) production in tumours." (PMID 38622286, 2024). "However, one of the limitations of this study was that no more experiments have been conducted to verify whether miR-301a-3p, RAB5A, and NFKBIA affect tumor progression." (PMID 36438897, 2022). "Neither NFKBIA nor DUSP22 mutations were found in any of the tumour samples or cell lines." (PMID 21951562, 2011). "Differentially gene expression analysis revealed 39 up‐regulated genes in tumours, including VEGFA, NFKBIA, S100A10 and C15orf48." (PMID 41275425, 2025). "The NFKBIA gene expression level was higher in the normal than in the cancer tissue in LUAD, LUSC, UCEC, and COAD patients; however, it was higher in the tumor than in the normal tissue in GBM patients." (PMID 38542508, 2024). "Among these five prognosis-related genes, we found that INHBA and CD24 were oncogenic genes, while GRAMD1C, NFKBIA and ACSS2 were tumour suppressor genes." (PMID 35999846, 2022). "NFKB1, NFKBIA, TNFRSF1A, and FASN were found to be related to DNA repair, which affects tumor sensitivity to DNA-damaging agents." (PMID 35899106, 2022). "As shown in the volcano plot, SU decreased GZMB expression and upregulated genes related to inflammatory activation (FOS, JUN, NFKBIA, DUSP2, JAK1, PIM1), tumor immunity (CD47, PCBP2, EIF5A, PDIA3, EGR1), and DNA damage (H2AFX, DDIT3, GADD45B)." (PMID 34824394, 2021). "Molecular analysis of excised tumors demonstrated that the treatment reduces tumor growth due to upregulation of forkhead box O1 (FOXO1) and NFKBIA (IκBα), thus activating apoptosis and potentially inhibiting NF-κB activity." (PMID 34572548, 2021). "CD24, CD74, PGK1 showed significantly higher expression in tumour tissue compared with tumour adjacent normal tissue, while STX11 and NFKBIA showed the opposite trend (p < .001 for all)." (PMID 34187256, 2021).
tumor (continued). "The genes most frequently showing CNGs in HAS tumour tissues were TOP1 (50.0%), STK4 (45.5%), CDKN1B (40.9%), H3F3A (36.4%), MYC (22.7%), CCNE1 (22.7%), NFKBIA (22.7%), VEGFA (18.2%), CCND3 (13.6%), and E2F1 (13.6%)." (PMID 30989433, 2019). "We found that the proteins were significantly modified compared to the control, and immune-related genes such as IL36RN, IL1RN, and NFKBIA were regulated by DAC, which suggested that the immunogenicity of the tumor cell was improved." (PMID 29622799, 2019). "We looked for correlations of EGFR amplification and/or NFKBIA deletion and overall survival (OS): four GBM were excluded from analysis as the patients died early after diagnosis for reasons unrelated to tumor progression." (PMID 24330732, 2013). "The tumor-suppressive outcome is driven by combined molecular changes: downregulation of SPARCL1 and PSME3, coupled with upregulation of the NF-κB inhibitor NFKBIA and downregulation of CD44 and CCL15, collectively promotes apoptosis while suppressing proliferation, migration, and angiogenesis." (PMID 41465234, 2025). "Furthermore, NFKBIA upregulation suppresses NF-κB survival signaling and activates SRC-FHIT tumor-suppressive pathways, and CCL15 downregulation diminishes chemotactic and angiogenic activity." (PMID 41465234, 2025). "The NFKBIA expression level was significantly (p < 0.001) higher in the normal than in the cancer tissue in LUAD, LUSC, UCEC, and COAD patients; however, it was significantly (p < 0.01) higher in the tumor than the normal tissue in GBM patients." (PMID 38542508, 2024). "Moreover, iv injection of TNF-α into the tail vein slightly upregulated NF-κB target genes (compared with the published articles), NFKBIA, and TNFAIP3, which were observed to examine the effect of TNF-α on the tumor NF-κB activity." (PMID 36110523, 2022). "The deletion or downregulation of NFKBIA is well associated with GBM progression and lack of response to therapies, in many types of cancers, suggesting the role of GA-T0 as a tumor suppressor." (PMID 34359676, 2021). "NK_c3 and NK_c5 were mainly derived from non-tumor liver tissues (23.57% and 5.97%, respectively) and characterized by high expression of transcription factors such as FOS, FOSB, FOXP1, and ATF4, and two genes involved in the NF-κB pathway, NFKBIA and NFKBIZ." (PMID 33298893, 2020). "However, in the CGC tumour tissues, the genes most frequently showing CNGs were CDKN1B (42.9%), H3F3A (23.8%), CDK2 (14.3%), NFKBIA (14.3%), and VEGFA (14.3%)." (PMID 30989433, 2019). "In vivo, we testified gene expression in xenograft tumor from control/u50535OE mice model and found that the u50535 overexpression can upregulate CCL20 and its following signal molecules such as CCR6, ERK, AKT, NFKBIA and so on." (PMID 29970882, 2018). "The deletion of NFKBIA (encoding nuclear factor of κ-light polypeptide gene enhancer in B-cells inhibitor-α), an inhibitor of the EGFR-signaling pathway, is reported to promote tumor development in GBM, which does not show mutations of EGFR." (PMID 27338365, 2016).
infection (243 papers, 2003 to 2026). The state of being infected such as from the introduction of a foreign agent such as serum, vaccine, antigenic substance or organism. "Both IKBKE and NFKBIA encode for inhibitors of NF‐κB and are involved in regulating inflammatory responses to infection." (PMID 35706367, 2022). "Pathways involved in chemokine receptor signaling were also significantly enriched, highlighting the recruitment of immune cells to the site of infection (NFKBIA, NFKBIB, NFKBIE, NFKBIZ, TNFAIP3, REL, BCL3)." (PMID 40634947, 2025). "NFKBIA had the highest expression of the top-correlated genes, and had high expression in the high infection cluster." (PMID 38961189, 2024). "NFKBIA knockout cells displayed a 31.8% decrease in infection, 85.5% in EIF4E2 KO, and 33.2% in EIF4H KO cells compared to non-targeting control cells." (PMID 37803001, 2023). "IFIT1 and DDX58 proteins increased from 24 to 48 hours post-infection while phosphorylated NFKBIA increased up to 32 hours post-infection in CTNNB1 knockdown cells." (PMID 23785285, 2013). "Infection with N-PRRSV also increased transcript abundance of NFKBIA, an inhibitor of the TNF receptor activated transcription factor NF-κB." (PMID 20614006, 2010). "We speculate that the NFKBIA gene might be an important gene for the S. nudus response to severe environmental conditions or pathogen infection." (PMID 37759582, 2023). "NFKBIA’s downregulation in PBMCs of severe patients may be due to localization of cells expressing NFKBIA to the site of infection in attempts to regulate the hyperactive inflammatory state." (PMID 35007307, 2022). "However, an enhanced upregulation of 9 genes, all involved in the NF-kB pathway (CCL2/MCP1, CCL20, CCL4, CXCL2/MIP2α, IL1A, NFKBIA, PTX3, TNFA, TNFAIP3), was observed after infection with D26 variants, in comparison to the WT." (PMID 33399033, 2021). "L. rhamnosus colonization alone or combined with C. albicans infection resulted in a marginal induction of cFOS, DUSP1, DUSP5 and NFKBIA expression at early time points, but L. rhamnosus colonization before infection downregulated these genes at later stages of infection." (PMID 31413153, 2019). "NF-κB is also one of the mediators involved in the acute phase response upon infection via degradation of the nuclear factor of kappa light polypeptide gene enhancer in B cells inhibitor alpha (NFKBIA), allowing activation of NF-κB by phosphorylation (p-NF-κB)." (PMID 29760677, 2018). "Interestingly, infection with H-PRRSV led to up-regulation of NFKBIA, an inhibitor of the TNF receptor activated transcription factor NF-κB." (PMID 20929578, 2010). "In addition to the cytokine and chemokine upregulation observed in this present work, the inflammatory response regulators SLAMF7, RELB, NFKBIZ, NFKBIA, and ZC3H12A were identified, further underlining the strong inflammatory response elicited by PCPEC during to infection." (PMID 33763387, 2021). "We further identified the NF-κB inhibitor IκBα (NFKBIA), as well as the translation factors EIF4E2 and EIF4H as strong host dependency factors acting early in infection." (PMID 37803001, 2023). "Per bin, the intron counts of the infection-induced genes IFIT2, OAS2, CCL5, IL6, NFKBIA, and TNF are shown, along with ATXN10 as control." (PMID 33585804, 2021). "TNFAIP3, PPP1R15A, NFKBIA, and IFIT2 had shown bimodal gene expression in various immune cells from severely infected patients compared to healthy or moderate infection cases." (PMID 33602138, 2021). "These signaling pathways showed that, after LPS infection, several DEGs were mainly related to immune function, such as up-regulated expression of CCL5, IL8, NFKBIA, TRAF3, and TNFAIP3, and down-regulated expression of MEF2C, MAP2K6, TLR1, TLR2, and IRF5." (PMID 34067819, 2021). "Specifically in the module, we find genes induced in response to infection such as IL1B, TNF, IL6, IL12B, NFKBIA, JUN, and MAP3K8, which are related to Toll-like receptor signalling (Appendix B)." (PMID 33498280, 2021).
infection (continued). "The NFKB2 and NFKBIA proteins are highly pleotropic but are best known for their involvement in the NFKB Pathway, a well-characterized pathway initiated during host infection." (PMID 33148169, 2020). "On the other hand, the caIBDV arrested the host's apoptotic process by inducing the expression of apoptosis inhibitors including NFKBIA/Z, TNFAIP2/3 and ITA at the first 12 hours of infection." (PMID 26053856, 2015). "Infection of wild type (WT) A549 cells with Sendai virus (SeV) or Zika virus (ZIKV) resulted in robust IFN-I (IFNB1) and IFN-III (IFNL1) transcription and activation of both IRF3-dependent (ISG54) and NF-κB-dependent (NFKBIA) genes." (PMID 38001254, 2024). "Additionally, miR-221-5p targeted NF-kappa B inhibitor alpha (NFKBIA) and Suppressor of cytokine signaling 1 (SOCS1), which promoted PEDV infection by inhibiting the production of IFN-β." (PMID 38257818, 2024). "Furthermore, in a ciliated cell line model, a very similar NF-kB-driven transcriptional signature (including NFKBIA, FOS and JUN) has been shown to be specifically induced in SARS-CoV-2-infected cells immediately (< 3 h) post-infection." (PMID 37700317, 2023). "The presence of NFKBIA re-synthesis during infection with MVA+AraC but not MVA infection also indicates a MVA blockade of the NF-κB pathway at or downstream of IκBs degradation." (PMID 38065956, 2023). "Further supporting this hypothesis, the upregulation of an NF-kB signature, including TNFAIP3, NFKBIA and FOS, was also induced in an epithelial cell line model 8 h after infection with SARS-CoV-2." (PMID 37700317, 2023). "Alternatively, NFKBIA re-synthesis could indicate that a protein, or proteins, expressed late in MVA infection results in the degradation of IκB, which is abrogated in the presence of AraC." (PMID 38065956, 2023). "Additionally, transcription of both the NFKBIA and TNFIAP3 genes were upregulated more in ΔescN and ΔnleH1, compared with wild-type and ΔnleH2 infections, also suggesting a role for NleH1 in transcriptional inhibition of these RPS3-dependent genes." (PMID 20041225, 2009). "We ranked the top 10 most upregulated and downregulated genes in each cellular subpopulation and noted the upregulation of inflammation-related genes, such as NFKBIA and NFKBID, suggesting that infection with H. contortus may induce an inflammatory response in the host." (PMID 38786064, 2024). "This was supported by the upregulation of the NF-kB inhibitor genes NFKBIA and NFKBIZ, the AP-1 transcription factor complex genes FOS, JUN, FOSB and JUNB as well as other NF-kB target genes such as TNFAIP3, RELB, NR4A2, DUSP1 and CD69 in response to infection." (PMID 37700317, 2023). "Moreover, during infection, genes involved in the regulation of the NF-κB cascade (AZI2, TBK1 and NFKBIA) and NFKB1were transcriptionally unaltered in all the respiratory tract of alpacas may be preventing acute inflammation in response to MERS-CoV." (PMID 34029358, 2021). "Meanwhile, anti-inflammatory factors such as TNFAIP3, NFKBIA, NFKBIZ, SOCS1, SOCS3, and IL-10 were elevated, with the reverse trends for the inflammation-inducing genes PPBP and MARCO at 38 hpi, suggesting that the pro- and anti-inflammatory responses might coexist in PAMs during YC-2020 infection." (PMID 36338035, 2022). "Compared to non-targeting controls, ACE2, NFKBIA, EIF4E2, and EIF4H knockout cell lines showed a substantial decrease in infection." (PMID 37803001, 2023).
cancer (242 papers, 2003 to 2026). A tumor composed of atypical neoplastic, often pleomorphic cells that invade other tissues. "NFIL3 promotes the progression of TNBC by suppressing NFKBIA transcription and then enhancing NF-κB signaling-mediated cancer-associated inflammation." (PMID 35180863, 2022). "Mutations, gene polymorphisms and haploid karyotypes of NFKBIA in various malignant tumors result in elevated NF-κB signaling activity and contribute to promoting the proliferation and metastasis of cancer cells." (PMID 35180863, 2022). "Both NFKBIA, and TANK are involved in NF-κB activation, and common polymorphisms in NFKBIA is associated with susceptibility to cancer." (PMID 33428680, 2021). "NFKBIA amplification and IκBα overexpression identify a unique cancer subtype associated with specific expression profile and metabolic signatures." (PMID 33863364, 2021). "Consistently, we observed that NFKBIA amplified cancers are also associated with a reduction in reactive oxygen species pathway." (PMID 33863364, 2021). "In the past few years, -881 A>G polymorphism of the NFKBIA gene has been a research focus in many cancer communities." (PMID 26252270, 2015). "Several epidemiological studies have focused on the role of nuclear factor-kappa-B inhibitor-alpha (NFKBIA) -881 A>G polymorphism in cancer susceptibility." (PMID 26252270, 2015). "Functional polymorphisms of NFKBIA, a known inhibitor of NF-κB, play an essential role in influencing NF-κB function, demonstrating the association of NFKBIA with NF-κB in several diseases, such as cancers." (PMID 40303498, 2025). "In general, whether NFKBIA mutations promote cancer initiation and/or progression through activation of NF-κB signaling or by alternative NF-κB-independent mechanisms in the different systems has not directly been analyzed." (PMID 34572464, 2021). "Interestingly, the transcriptional profile showed evidence of significant inverse correlation with the signature of apoptotic response associated genes, suggesting that the role of NFKBIA in cancer is far from being clarified." (PMID 33863364, 2021). "Numerous studies have suggested that polymorphisms in genes encoding inflammatory response factors, such as TNF-alpha -308G>A, IL6 -174G>C, and NFKBIA -826C>T may contribute to cancer susceptibility." (PMID 28039461, 2017). "Genetic variation in the promoter region of NFKBIA, which alters the ‘tuning’ of stress and immune responsiveness, has been linked to alterations in susceptibility to infectious and inflammatory diseases, and a variety of cancers." (PMID 24066085, 2013). "Functional pathway of “Molecular Mechanism of Cancer” was indirectly influenced by activated NFKBIA, bone morphogenetic protein 10 (BMP10), RB transcriptional corepressor like 2 (RBL2) and RELA." (PMID 39342193, 2024). "Key targets such as TNF, PTGS2, PRKACA, HSP90AB1, RELA, and NFKBIA appeared to be involved in chemical carcinogenesis–receptor activation, pathways in cancer, IL-17 signaling pathway, cholinergic synapse pathway, and regulation of lipolysis in adipocytes." (PMID 39064924, 2024). "NFKBIA is a member of the NF-κB family that is closely related to head and neck, nasopharyngeal, and other cancers." (PMID 37056763, 2023). "To further investigate NFKBIA amplification in cancer, we profiled NFKBIA copy number in a total of 480 human cell lines." (PMID 33863364, 2021). "Using the Pancan12 TCGA data set, which includes 32 studies and 10,967 cancers of different histotypes, we measured NFKBIA (the gene coding for IκBα) copy number variations, revealing several cases of amplification in cancer." (PMID 33863364, 2021). "Some of these genes were also present in the general cancer pathway, including NFkBIA, IL-6 and CXCL8." (PMID 34680349, 2021). "These genes include known and novel FOXL2 targets (TGFB2, SMARCA4, HSPG2, MKI67, NFKBIA) and are enriched for neoplastic pathways (Proteoglycans in Cancer, Chromatin remodeling, Apoptosis, Tissue Morphogenesis, Tyrosine Kinase Receptors)." (PMID 33639972, 2021).